IL5 (interleukin 5)
Diseases named in the same sentence as IL5 in open-access papers (continued):
Sharing a sentence is not in itself a finding about the gene and the disease.
asthma (continued). "Cytokines produced by the Th2-type CD4 + T cells (interleukin (IL-4, IL-5, IL-13) in asthma have a central role in orchestrating the inflammatory response." (PMID 25890178, 2015). "Inflammatory cytokines such as IL-4, IL-5 and IL-13 are induced in the lung during asthma exacerbations." (PMID 26048391, 2015). "MiR-126 has also been found to be upregulated in the airway of an asthma mouse model, and its suppression reduces inflammation, expression of Th2 cytokines (e.g., IL-5 and IL-13), and airway hyperreactivity." (PMID 26418311, 2015). "Consistent with prior studies, our results also demonstrate that subjects with asthma have higher concentrations of IL-5 and the numbers of eosinophils in BAL fluid compared to control subjects." (PMID 26011707, 2015). "The low detection rate of IL-5 corresponds to our finding that IL-5 has limited power to predict an asthma exacerbation." (PMID 25799487, 2015). "IL-5 is essential for the maturation of eosinophils, and it accumulates in the lung during the inflammatory process of asthma." (PMID 26101464, 2015). "Mouse models of asthma support the roles of IL-4, IL-5, and IL-13 in disease development, as knockout mice for these cytokines show reduction in overall asthma symptoms." (PMID 26346739, 2015). "Antigen-activated CD4+ T cells induce several characteristic features of asthma, including the secretion of Th2-type cytokines such as IL-4, IL-5, and IL-13, which are responsible for IgE production by B cells and eosinophil activation and recruitment." (PMID 26385707, 2015). "Th2 cells distinguish themselves from other T cell subsets by secreting IL-4, IL-5, and IL-13; they actively promote IgE antibody production and regulate the immune response to allergens, including those involved in asthma and parasitic infections." (PMID 26065426, 2015). "In analogy, compound A has been shown to inhibit the OVA-induced IL-4 and IL-5 Th2 cytokine production in bronchoalveolar lavage fluid in a murine model of OVA-induced asthma." (PMID 25875480, 2015). "By contrast, compared to eosinophil-normal asthma (eosinophils≤0.3%), eosinophil-high asthma (eosinophils>0.3%) had higher levels of IL-5, IL-13, IL-16, and PDGF-bb, but same neutrophil percentage, IL-8, and FEV1." (PMID 26011707, 2015). "Third, regarding cytokine biomarkers in sputum samples, IL-8 and IL-5 concentrations were assessed in (induced) sputum samples of asthmatic children during and 2 weeks after recovery of an acute asthma exacerbation." (PMID 25799487, 2015). "Careful enumeration of the levels of IL-4, IL-5, and IL-13 together and the levels of eosinophils in serum and tissue can classify asthma endotypes into Th2hi and Th2lo subsets." (PMID 26346739, 2015). "Compared to Eos-Normal asthma, Eos-High asthma had higher levels of IL-5 (p<0.05), IL-13 (p<0.05), IL-16 (p<0.05), and PDGF-bb (p<0.05), but same % neutrophils, IL-8, other cytokines (data not shown), and FEV1." (PMID 26011707, 2015). "In CRSwNP, there is an increase in the Th2 cytokines like IL-4, IL-5 and IL-13 and the intensity of eosinophils in the tissues of these patients is markedly increased in the presence of co-existing asthma or positive allergy skin tests." (PMID 25379119, 2014). "HDM-specific IL-5 responses at age 3 years or later are the best measure of T cell function for predicting asthma at age 8 years." (PMID 24875149, 2014). "Th2 cytokines such as IL-4, IL-5, and IL-13 play an important role in the pathophysiology of asthma, including AHR and airway wall remodeling." (PMID 25180025, 2014). "As antibody array showed that mangiferin suppressed characteristic cytokines secreted by Th1/Th2 cells such as IFN-γ, IL-12 and IL-4, IL-5, IL-13, which played the key roles in asthma." (PMID 24955743, 2014). "In our model of asthma SOCS3-siRNA treatment produce also a decreased expression in IL-5, IL-13, and IL-4." (PMID 24637581, 2014).
asthma (continued). "In asthma, there seems to be an increased expression of Th2 cytokines, with an elevated production of IL-4, IL-5 and IL-13." (PMID 24450480, 2014). "The first randomized controlled trials with anti-IL-5 were conducted in patients with mild to moderate asthma." (PMID 26557245, 2014). "Th2 cells, which are characterized by IL-4, IL-5, IL-9 and IL-13 cytokine production, predominate in asthma, whereas Th1 cells producing IFN-γ, IL-2 and TNF have rarely been associated with asthma." (PMID 25132806, 2014). "The elevated serum levels of IL-4, an essential cofactor for immunoglobulin E (IgE) production, and IL-5, responsible for the final differentiation, activation and recruitment of eosinophils, have been found in patients with asthma." (PMID 24450480, 2014). "Similar to previous studies, we also observed pleiotropy for a number of loci in particular PTPN22 for JRA, T1DM, and Thyroiditis, IL5 for Eosinophilia, Asthma, and EoE and NDFIP1 for Mental Retardation traits and Cerebral Palsy." (PMID 25477900, 2014). "Targeting Interleukin-5 (IL-5) in asthma, the central protagonist in eosinophilia (discussed in details later), was a logical derivative post promising results in animal models and initial screenings in patients." (PMID 25709744, 2014). "The mixed outcomes from anti-IL-5 clinical trials highlight the need for careful endotyping of patients, since the therapy is deemed effective on those patients whose asthma is dependent on the eosinophilic inflammatory pathway." (PMID 25709744, 2014). "The pathogenesis of asthma has been related to an imbalance of cytokines released from T helper (Th) cells, with an increase in Th2 type cytokines (Interleukin (IL) IL-4, IL-5, and IL-13) and a decrease in Th1 cytokines (IFN-γ and IL-2)." (PMID 24450480, 2014). "In humans with asthma, morphological and inflammatory changes are accompanied by increases in lung IgE, IL-4, IL-5, and IL-13." (PMID 24723965, 2014). "Asthma is thought to occur due to over-expression of Th2 cytokines such as interleukin (IL)-4, IL-5, and IL-13." (PMID 24886260, 2014). "They further identified patients with distinctly higher levels of IL-5 and IL-13, termed Th2-high asthma." (PMID 26557245, 2014). "The results indicated that Th2 cytokines (IL-4, IL-13, and IL-5) were increased in mice with chronic-induced asthma (P<0.05) when compared with saline mice." (PMID 24637581, 2014). "The clinical significance of this finding is highlighted by the observation that therapy with an anti-IL-5 antibody has beneficial effects, including a reduction in exacerbation frequency, in a selected subgroup of adults with severe asthma." (PMID 24875149, 2014). "The cytokine profile in asthma is typified by interleukin (IL-) 4, IL-5, and IL-13 that are typical Th2 cytokines." (PMID 24637581, 2014). "Mepolizumab is an antibody that binds IL-5, used in the therapy of hypereosinophilic syndromes and asthma." (PMID 23533306, 2013). "In severe asthma, an 8 and 33-times higher Il5 and Il6 expressions, respectively, was observed in allergen-sensitized and challenged mice but not in control, sensitized only, and challenged only mice." (PMID 23781124, 2013). "IL-4 induces class switching and release of IgE by B cells, and IL-5 plays an important role in the induction of the eosinophil influx into the lungs in allergen-driven models of asthma." (PMID 23451035, 2013). "In severe asthma, the largest change (110-fold) is observed in Ifnγ expression followed by Il13, Il2, Il4, Il10, Il6, Il5, and Tnfα, respectively." (PMID 23781124, 2013). "Both IL-1α and IL-1β, for example, are known to be molecules with a strong proinflammatory role, IL-15 has been reported to be elevated in celiac patients in previous studies, and IL-5 plays an important role in the pathophysiology of asthma." (PMID 23533306, 2013).
asthma (continued). "Several placebo-controlled clinical trials have evaluated the efficacy and safety of mepolizumab, a humanized monoclonal antibody against IL-5, in patients with asthma." (PMID 23544105, 2013). "Th2 lymphocytes play an important role in the initiation and progression of allergic diseases, including asthma, by releasing IL-4, IL-5, and IL-13." (PMID 23843865, 2013). "IL-10 is produced by macrophages and by a subset of regulatory T cells (Tregs) and exerts its effects by inhibiting the synthesis of inflammatory cytokines (including asthma-associated cytokines such as TNF-α and IL-5) and gene presentation." (PMID 23781124, 2013). "It seems, however, that for the majority of asthmatic patients the anti-IL-5 treatment will need to be administered in combination with other therapies that suppress asthma features through other mechanisms." (PMID 24032029, 2013). "In the present study, we combined data that evaluated the efficacy of mepolizumab, a monoclonal antibody to IL-5, in patients with asthma." (PMID 23544105, 2013). "In Th2 cell-driven murine asthma models, mucus production and eosinophilia depend on IL-13 and IL-5." (PMID 23976880, 2013). "Most anticytokine strategies under current development for the treatment of asthma mainly target Th2-derived cytokines, including IL-5, IL-4, and IL-13, crucially involved in the pathobiology of allergic phenotypes." (PMID 23853765, 2013). "In mild asthma, Tbet expression was significantly correlated with Il2, Il4, Il5, Il6, Il13, and Tnfα expression." (PMID 23781124, 2013). "Interleukin-5 is involved in a number of immune responses such as asthma, helminth infection, and sepsis." (PMID 23472217, 2013). "The concept of using anti-IL-5 to treat asthma was first investigated in animal models in which anti-IL-5 antibodies were shown to successfully reduce allergen-induced airway eosinophilia." (PMID 23828644, 2013). "Additional larger studies will be required to establish the possible role of anti–IL-5 as a therapy for asthma." (PMID 23544105, 2013). "The studies demonstrate that anti-IL-5 therapy is effective in reducing exacerbation frequency in severe asthma, with highest efficacy in subgroups of patients where eosinophils have a pathogenic role." (PMID 24032029, 2013). "Previous clinical trials have evaluated the efficacy and safety of mepolizumab, a monoclonal antibody against IL-5, in patients with asthma." (PMID 23544105, 2013). "GMCSF, IFN-γ, IL-5, IL-8 and IL-10, on the other hand, were significantly decreased in children with asthma (p 0.003, 0.03, 0.001, 0.004 and 0.03, respectively)." (PMID 23286340, 2013). "For instance, humanized antibodies that ameliorate TH2 effector pathways by blocking circulating IgE (omalizumab) or IL-5 (mepolizumab) reduced exacerbations and need for other medication and improved asthma control." (PMID 24223970, 2013). "We observed an increase in the level of IL-1β, IL-4, IL-5, IL-6, IL-8, and IL-10 in asthma patients as compared to the controls." (PMID 23226977, 2012). "In asthma and allergic diseases, eosinophil recruitment, survival, and cytotoxic effector functions are largely regulated by IL-5 family cytokines (IL-3, IL-5, GM-CSF)." (PMID 22838633, 2012). "In OVA and house dust mite- (HDM-) induced experimental asthma, ILCs2 are the main source of IL-5 and IL-13 production." (PMID 23209480, 2012). "Considering the central role of IL-5 in eosinophil biology and in the pathophysiology of asthma, we investigated the effect of H89 in mouse models of asthma." (PMID 23189147, 2012). "IL5 is an accepted marker for the Th2 subset, which stimulates humoral responses, but is also involved in allergy and asthma." (PMID 23056616, 2012). "IL-5 was identified as a target to prevent or blunt eosinophil-mediated inflammation in patients with asthma, leading to the development of humanized anti-IL-5 mAb such as mepolizumab, reslizumab and benralizumab." (PMID 23189057, 2012).
asthma (continued). "Increased levels of sputum eosinophils and sputum IL-5, increased peripheral blood mononuclear cell-derived TNF-α, IL-12, and decreased IFN-γ levels were associated with on-going asthma symptoms and airway hyperresponsiveness." (PMID 23043798, 2012). "It is evident from the results of the present study and those reported in the literature that IL-5 plays a role in asthma by interacting with other inflammatory mediators." (PMID 23226977, 2012). "Increased IL-8 and decreased IL-5 is a pattern also seen asthma and in B cell chronic lymphocytic leukemia (B-CLL)." (PMID 22973830, 2012). "Compared with the control group, the CVA and classic asthma groups were found to have higher baseline levels of IL-5 and percentage of EOS in addition to lower concentrations of IL-10 in induced sputum." (PMID 22927709, 2012). "Previous studies have found that excessive secretion of Th2 cytokines, including IL-4, IL-5, and IL-13, is able to aggravate pathological asthma symptoms." (PMID 23049614, 2012). "Activated Th2 cells are prolific sources of IL-4, IL-5, and IL-13, among other cytokines, each of which has been suggested to play a role in asthma pathogenesis." (PMID 23043798, 2012). "Our data suggest that the therapeutic effects of CF in asthma are mediated by reduced production of Th2 cytokines (IL-5), eotaxin, and OVA-specific IgE and reduced eosinophil infiltration." (PMID 22439901, 2012). "Our data suggest that the therapeutic mechanism by which HPN effectively treats asthma is based on reductions of Th2 cytokines (IL-5), eotaxin, OVA-specific IgE production, and eosinophil infiltration via inhibition of GATA-3 transcription factor." (PMID 21772663, 2011). "For example, sputum eosinophilia predicts corticosteroid responsiveness and the response to the anti-IL-5 blocker mepolizumab in severe asthma." (PMID 21896202, 2011). "Further, asthma is largely characterized as a Th2 mediated disease, accompanied by high IL-4 and IL-5 production and low IFNγ." (PMID 21345191, 2011). "IL-5 is vital for the growth, differentiation, recruitment, and survival of eosinophils which contribute to inflammation and even airway remodeling in asthma." (PMID 21695271, 2011). "Two recent exploratory studies have examined anti-IL5 monoclonal antibody (mepolizumab) treatment in patients with severe asthma." (PMID 21896202, 2011). "CD4+ T helper type 2 (TH2) cytokines such as IL-4, IL-5 and IL-13 play a critical role in inducing allergy and asthma." (PMID 22014099, 2011). "Th2 cytokines also activate secondary effector cells in asthma including the recruitment of mast cells (IL-4, IL-9 and IL-13) and basophils (IL-3 and IL-4), whilst IL-5 supports growth, differentiation, and activation of eosinophils." (PMID 19769993, 2010). "Besides its affects on differentiating B cells IL-5 predominantly works on eosinophils by effecting their differentiation, recruitment, activation, and survival in the periphery predisposing this cytokine as a central factor in regulating airway eosinophilia in asthma." (PMID 20976014, 2010). "IL-12 (p40), IL-5, and IFNγ/IL-5 showed differences between the extrinsic and intrinsic asthma phenotype." (PMID 21179211, 2010). "In contrast to IL-12, a substantial body of data in mice and humans support the importance of IL-5 in asthma." (PMID 21179211, 2010). "Evidence for effective induction of asthma-like allergic airway inflammation was sought: ovalbumin-treated mice developed marked airspace eosinophilia and IL-5 up-regulation, widely used biomarkers of asthma." (PMID 20796309, 2010). "Regulatory differences between parental and pediatric asthma were reflected by six of the eleven mediators analyzed (eotaxin, IL-4, IL-5, IL-10, IL-12, TNFα)." (PMID 21179211, 2010). "In Alternaria-sensitive moderate-severe asthma, Alternaria extract stimulated lymphocytes had significantly increased synthesis of IL-5 and IL-13 compared to Alternaria-sensitive mild asthma (p = 0.008 and p = 0.004, respectively)." (PMID 20298583, 2010).
asthma (continued). "IL-12 (p40) and IL-5 were the best predictor for extrinsic asthma in children with an increased odds ratio of 2.85 and 1.96 per log pg/ml increase (IL-12 (p40): 1.2–6.8, p = 0.019, and IL-5: 1.2–2.5, p = 0.025)." (PMID 21179211, 2010). "IL-12 and IL-5 demonstrate only moderate marker characteristics to distinguish between the extrinsic and intrinsic asthma phenotype." (PMID 21179211, 2010). "By secreting a plethora of typical mediators such as interleukin (IL) 4, IL-5, and IL-13, these cells hold a key position in asthma pathogenesis." (PMID 20976014, 2010). "Further, peripheral blood mononuclear cells (PBMCs) from asthma patients produced significantly higher IL-5 protein levels on stimulation with C. albicans than those from non-allergic patients in vitro, implicating a role in the exacerbation of asthma." (PMID 19619338, 2009). "Elevated levels of type 2 T cell cytokines such as IL-4, IL-5 and IL-13 are recognized as factors that initiate and accelerate allergic inflammation in asthma." (PMID 19531238, 2009). "Inflammation in allergic diseases such as asthma, rhinitis, and atopic dermatitis is mediated via expression of the cytokines interleukin (IL)-4, IL-5, and IL-13 from T helper-2 (Th2) cells." (PMID 19436703, 2009). "In recent studies RNA interference using a short hairpin RNA, has been able to block IL-5Rα expression, decrease bone marrow eosinophilopoiesis and blood and BAL eosinophilia in an animal model of asthma showing new potential blockers of IL-5 function." (PMID 18315837, 2008). "Suplatast tosilate is a novel oral anti-asthma compound that, in vitro, selectively inhibits IL-4 and IL-5 production from allergen-stimulated human Th2 lymphocytes, but not IFN-γ production from human Th1 lymphocytes." (PMID 18315837, 2008). "Th2-type T cells secreting a distinctive set of cytokines [such as interleukin (IL)-4, IL-5 and IL-13] play a pivotal role in asthma." (PMID 18489791, 2008). "The 5q23.2-q34 region contains the cytokine gene cluster (IL4, Il13, IL5, IL12B) and has previously been suggested as an asthma/atopy susceptibility locus and the 7p21.1-14.1 region contains the previously identified asthma susceptibility gene, GPRA (7p14.3)." (PMID 18442398, 2008). "IL-5 knockout mice appeared to confirm a role in asthma models where eosinophilia and AHR is markedly suppressed." (PMID 18315837, 2008). "We and others have showed that IL-5 transcripts are detectable in the lungs of patients with asthma, dominantly derived from the T cell fraction." (PMID 18489791, 2008). "The present data emphasize the essential role of Th2 cell produced IL-4 and IL-5 in the induction of asthmatic clinical symptoms in patients with CRS-asthma." (PMID 16677400, 2006). "Significant correlation has been identified between high levels of interleukin (IL)-4 and IL-5 and clinical severity of asthma." (PMID 16677400, 2006). "Administration of IL-12 at the time of a single antigen challenge abolished airway hyper-responsiveness and pulmonary eosinophilia, and promoted increased IFN-γ and decreased IL-4 and IL-5 expression, in mice sensitized for asthma with ovalbumin." (PMID 16396683, 2006). "In chronic allergic diseases such as asthma, during continuous antigen exposure, eosinophils are primed by IL-5 and attracted by chemokines, infiltrating the local tissue." (PMID 15745456, 2005). "Production of IL-5, a cytokine considered particularly relevant in asthma, was significantly reduced following PIT." (PMID 15783262, 2005). "Current research on IL-5 focuses on its link with MP-induced wheezing or asthma." (PMID 41313182, 2026). "The mechanism of Type 2 inflammatory asthma: Upon allergen exposure in the airways, dendritic cells (DCs) present processed allergens to Th2 lymphocytes, which subsequently secrete interleukin‐5 (IL‐5), IL‐4, and IL‐13." (PMID 41310922, 2025). "The fact that a patient developed asthma only in adulthood may be a good marker of the response to anti-IL5 therapies." (PMID 40364184, 2025).